CRACR2A (calcium release activated channel regulator 2A)
Description:
[Isoform 1]: Ca(2+)-binding protein that plays a key role in store-operated Ca(2+) entry (SOCE) in T-cells by regulating CRAC channel activation. Acts as a cytoplasmic calcium-sensor that facilitates the clustering of ORAI1 and STIM1 at the junctional regions between the plasma membrane and the endoplasmic reticulum upon low Ca(2+) concentration. It thereby regulates CRAC channel activation, including translocation and clustering of ORAI1 and STIM1. Upon increase of cytoplasmic Ca(2+) resulting from opening of CRAC channels, dissociates from ORAI1 and STIM1, thereby destabilizing the ORAI1-STIM1 complex. [Isoform 2]: Rab GTPase that mediates the trafficking of Weibel-Palade bodies (WPBs) to microtubule organizing center (MTOC) in endothelial cells in response to acute inflammatory stimuli. During histamine (but not thrombin) stimulation of endothelial cells, the dynein-bound form induces retrograde transport of a subset of WPBs along microtubules to the MTOC in a Ca(2+)- independent manner and its GTPase activity is essential for this function. Ca(2+)-regulated dynein adapter protein that activates dynein-mediated transport and dynein-dynactin motility on microtubules and regulates endosomal trafficking of CD47. Acts as an intracellular signaling module bridging two important T-cell receptor (TCR) signaling pathways, Ca(2+)-NFAT and JNK, to affect T-cell activation. In resting T-cells, is predominantly localized near TGN network in a GTP-bound form, upon TCR stimulation, localizes at the immunological synapse via interaction with VAV1 to activate downstream Ca(2+)-NFAT and JNK signaling pathways. Plays a role in T-helper 1 (Th1) cell differentiation and T-helper 17 (Th17) cell effector function. Plays a role in store-operated Ca(2+) entry (SOCE) in T-cells by regulating CRAC channel activation.
Synonyms: EFCAB4B; RAB46; MGC4266
Tractability: Antibody: UniProt places it where antibodies can reach, with high confidence; its Gene Ontology location is reachable by antibodies, with high confidence. PROTAC: ubiquitination databases record sites on it; its protein half-life has been measured; a small molecule that binds it is known.
Gene: Protein-coding gene on chromosome 12 (3,606,633 to 3,764,819, reverse strand). Ensembl gene ENSG00000130038.
Subcellular location: Cytoplasm (Isoform 1); Cytoplasm (Isoform 2); Cytoplasm, cytoskeleton, microtubule organizing center; Cell membrane; Golgi apparatus membrane; Golgi apparatus, trans-Golgi network membrane; Vesicle
Pathways (Reactome):
Immune System: Neutrophil degranulation
Gene Ontology:
Molecular function: calcium ion binding; GTPase activity; protein binding; GTP binding; G protein activity
Biological process: activation of store-operated calcium channel activity; intracellular protein localization; positive regulation of calcium ion transport; store-operated calcium entry; establishment of localization in cell; leukocyte activation involved in immune response; vesicle-mediated transport
Cellular component: cytoplasm; Golgi membrane; membrane; plasma membrane; vesicle; extracellular region; specific granule lumen; bounding membrane of organelle; Golgi apparatus; microtubule organizing center; specific granule
Genetic constraint (gnomAD): Loss-of-function variants: 76 observed, 94.93 expected, observed/expected ratio (o/e) 0.8, 90% interval 0.66 to 0.97. The upper end of that interval is the gene's LOEUF score, 0.97, which puts it in group 4 of 6, group 1 being the genes least tolerant of losing a copy. Missense variants: 823 observed, 936.27 expected, observed/expected ratio (o/e) 0.88, 90% interval 0.83 to 0.93. Synonymous variants: 338 observed, 376.09 expected, observed/expected ratio (o/e) 0.9, 90% interval 0.82 to 0.98.
Gene-disease validity (ClinGen):
ClinGen rates the evidence that CRACR2A causes each of these diseases.
combined immunodeficiency (autosomal recessive): Limited.
Homologues: Orthologues: chimpanzee CRACR2A (99% identical), macaque CRACR2A (96% identical), rabbit CRACR2A (84% identical), dog CRACR2A (82% identical), guinea pig CRACR2A (82% identical), mouse Cracr2a (80% identical), pig CRACR2A (80% identical), rat Cracr2a (80% identical), tropical clawed frog CRACR2A (52% identical), zebrafish CRACR2A (52% identical), zebrafish cracr2ab (49% identical). Paralogues in human: CRACR2B (19% identical).
Diseases named in the same sentence as CRACR2A in open-access papers:
CRACR2A is named in the same sentence as 31 diseases in open-access papers, as found by Europe PMC text mining. Sharing a sentence is not in itself a finding about the gene and the disease. The quoted sentences say what the papers report.
Immunodeficiency (3 papers, 2021 to 2025). Failure of the immune system to protect the body adequately from infection, due to the absence or insufficiency of some component process or substance. "Here, we describe a single case of late onset combined immunodeficiency due to biallelic variants in CRACR2A which encodes CRACR2A." (PMID 34908525, 2021). "However, whilst a patient with biallelic mutations in EFCAB4B, where neither Rab46 or CRACR2A is expressed, displayed immunodeficiency due to a loss of function in T-cells, CRACR2A expression in neutrophils promotes neutrophil migration in inflammation." (PMID 40034259, 2025). "There are plenty of regulatory proteins, including CRACR2A, SEPTIN4, STIMATE, GOLLI, SARAF, ORMDL3 and so on, that contribute to alter SOCE activity in cancer, immune diseases and inflammation disorders." (PMID 36128650, 2022).
immunodeficiency disorders (3 papers, 2021 to 2025). "Given the resultant clinical phenotype and range of associated immunological abnormalities, we propose that CRACR2A deficiency should be included within the group of combined immunodeficiency disorders in the IEI classification." (PMID 34908525, 2021).
breast carcinoma (2 papers, 2022 to 2023). "CRACR2A was also required to support migration of MDA-MB-231 breast cancer cells (which lack Rab25 expression, but express high levels of CRACR2A) in the 3D CDM." (PMID 37232246, 2023).
combined immunodeficiency (2 papers, 2021 to 2025). A broad classification of inherited disorders presenting at birth that affect both the cell-mediated and humoral aspects of the immune response. "Thus, we have identified variants in CRACR2A that led to late-stage combined immunodeficiency characterized by loss of function in T cells." (PMID 34908525, 2021).
male infertility (2 papers, 2020 to 2022). The inability of the male to effect fertilization of an ovum after a specified period of unprotected intercourse. "In total, we found nine genes that were recorded to be associated with “male infertility” or “non-obstructive azoospermia,” and three of them (CLASP2, CRACR2A, SOX5) were identified in this study as zebrafish testis cell-type specific marker genes." (PMID 35360857, 2022).
channelopathies (1 paper, 2024). "In comparison, relatively few of these channelopathies have been documented to specifically affect the immune system, and these channelopathies are principally due to recessive or biallelic variants in ORAI1, STIM1, or the recently described regulatory protein CRACR2A." (PMID 39270020, 2024).
colon cancer (1 paper, 2023). "Accordingly, both technologies reported the overexpression of STIM1, MBP, SEPTIN9, and SEPTIN10 and the downregulation of CRACR2A, ORMDL3, SARAF, SEPTIN3, and SEPTIN6 in colon cancer cells." (PMID 36900391, 2023).
lung carcinoma (1 paper, 2021). "Genetic analysis of the human genome indicated that Rab46 is an inducible protein, since exercise causes hypomethylation of the promoter region of the CRACR2A gene, resulting in lower risk of metastatic prostate cancer and lung cancer." (PMID 34299309, 2021).
lymphopenia (1 paper, 2021). Reduction in the number of lymphocytes. "Consequently, our investigations have focused on the function of T cells, and in particular CD4+ cells due to the known role of CRACR2A in their activation and also progressive selective CD4+ lymphopenia which was evident from the patient’s phenotype." (PMID 34908525, 2021). "However, our results do not exclude the possibility that CRACR2A can play a role in activation of other innate and adaptive immune cell types, which may have indirect contribution to lymphopenia observed in the patient." (PMID 34908525, 2021).
microcephaly (1 paper, 2021). A congenital or acquired developmental disorder in which the circumference of the head is smaller than normal for the person's age and sex. "Among patients sharing microcephaly a common deleted region of ~ 300 kb in 12p13.32 locus containing two genes CRACR2A (HGNC: 28657) and PRMT8 (HGNC: 5188) could be identified." (PMID 33613193, 2021). "Among patients sharing microcephaly a common deleted region in 12p13.32 locus of ~ 300 kb containing two genes CRACR2A (HGNC: 28657) and PRMT8 (HGNC: 5188) could be identified." (PMID 33613193, 2021).
nonalcoholic fatty liver (1 paper, 2021). "A genome-wide association study indicated that four single-nucleotide polymorphisms in CRACR2A/Rab46 (EFCAB4B) caused periodontal diseases, and nonalcoholic fatty liver (NAFL) and/or nonalcoholic liver disease (NAFLD)." (PMID 34299309, 2021).
primary immunodeficiency (1 paper, 2021). "Our study describes a novel cause of primary immunodeficiency in humans due to compound heterozygous mutations in CRACR2A." (PMID 34908525, 2021). "However, until now, CRACR2A has not directly been linked with a primary immunodeficiency (PID) in humans." (PMID 34908525, 2021).
prostate carcinoma (1 paper, 2022). A carcinoma that arises from epithelial cells of the prostate gland. "A recent study also reported hypermethylation of CRACR2A in prostate cancer tissue from men with metastatic‐lethal disease, at a region overlapping the promoter DMR identified in our study." (PMID 36178085, 2022).
cancer (3 papers, 2021 to 2022). A tumor composed of atypical neoplastic, often pleomorphic cells that invade other tissues. "Previous studies have shown that EGR1, TMEM79, and CRACR2A are closely related to the progression of a variety of cancers, and it is worthwhile to further explore their molecular mechanisms." (PMID 34853602, 2021). "In this study, we have demonstrated that the up-regulation of MUC2, SEC16A and CRACR2A is the common denominator of all carcinomas with mucinous differentiation studied here." (PMID 33947930, 2021). "The intersection of these lists revealed that three genes (MUC2, CRACR2A, SEC16A) were significantly up-regulated in carcinomas-muc of all tested cancer types compared to controls." (PMID 33947930, 2021).
CRACR2A also shares sentences with these, for which no sentence is quoted: Allergy (1 paper); Anhidrotic ectodermal dysplasia (1); Azoospermia (1); cardiovascular disease (1); COVID-19 (1); glycogenosis (1); Hepatic steatosis (1); infection (1); Infertility (1); liver disease (1); male fertility (1); metabolic disorders (1); metastatic prostate carcinoma (1); non-alcoholic fatty liver disease (1); osteopetrosis (1); pulmonary veno-occlusive disease (1); tumour (1).